CASP9 (caspase 9)
Diseases named in the same sentence as CASP9 in open-access papers (continued):
Sharing a sentence is not in itself a finding about the gene and the disease.
tumor (continued). "Besides, higher expressions of Cyt C and associated caspase-9 and 3 were observed in response to CANE signifying its apoptotic role in the tumor." (PMID 29317755, 2018). "Moreover, oridonin dose-dependently increased the ratio of Bax/Bcl-2 and the cleavage of Caspase-3 and Caspase-9 in tumor tissues." (PMID 29323103, 2018). "We then performed hematoxylin and eosin (H&E) staining and immunohistochemical analysis of tumor tissues and found that compared with etoposide treatment alone, tumor tissues simultaneously treated with melatonin and etoposide showed significantly higher caspase-9 and caspase-3 expression." (PMID 30201872, 2018). "Moreover, we investigated the effect of CNTD2 overexpression on three markers of apoptosis (cleaved PARP1, Bax and caspase 9) in resected tumours." (PMID 30087414, 2018). "We observed that caspase-9 was consistently lower in human tumor than in control tissue." (PMID 30680070, 2018). "Moreover, expressions of the cleaved caspase-3, caspase-9 in tumor sections were also increased by kurarinone-treated xenograft mice model." (PMID 29628889, 2018). "In conclusion, our results provide suggestive evidence that CASP9 and CASP3 genetic polymorphisms may be independent prognosis markers for HCC patients with surgical resection of tumor." (PMID 28453560, 2017). "In conclusion, the remarkable effects of ASC on the induction of apoptosis through caspase-9 activation and gap junctions may have important bearings in tumor suppression and represent a promising new target in anticancer therapy." (PMID 28056049, 2017). "Finally, cytochrome c was released rapidly from the mitochondria into cytoplasm and initiated the activation of apoptosis-related proteins such as caspase-9 and caspase-3, eventually inducing significant apoptosis of tumor cells." (PMID 28249375, 2017). "NAP also noticeably upregulated cleaved-caspase 3 and cleaved-caspase 9 levels in tumor cells." (PMID 28686182, 2017). "Furthermore, marked downregulation of FLIP levels and increased cleavage forms of caspase 9/PARP were observed in tumor homogenates." (PMID 26587975, 2016). "The expression of apoptotic genes, such as caspase-3 and caspase-9, was decreased in tumor-bearing rats as compared to the normal control rats, whereas DEN-induced rats treated with 1,3-BPMU displayed significantly increased caspase-3 and caspase-9 expression as compared to the tumor-bearing rats." (PMID 27187346, 2016). "The possible underlying mechanism is that the expression of MUC4 could inhibit apoptosis by the activation of caspase-9, which further resulted in the development of drug resistance in tumor cells." (PMID 26673820, 2016). "In agreement with the role of caspase-mediated apoptosis in tumor biopsies, we observed increased expression of caspase-9 and caspase-3 transcripts in tumor tissue from mice injected subcutaneously with HCMV-infected HepG2 cells but not from the control groups using RT-PCR assay." (PMID 27626063, 2016). "The western blot results revealed that EF24 decreased the expression of XIAP and increased the expression of cleaved caspase-9 and caspase-3.The positive tumor cells for Ki-67, a cell proliferation marker, were substantially less in tumors treated with EF24, compared with control tumors." (PMID 27571770, 2016). "Expression of caspase-9 was not predictive of OS (p = 0.275, log rank test), however, patients with tumours expressing low levels of caspase-9 protein had a strong trend towards a worse RFS than patients with tumours expressing high levels of caspase-9 protein (p = 0.054, log rank test)." (PMID 25157404, 2014).
tumor (continued). "Patients with tumours expressing low levels of caspase-9 protein had a trend towards a worse RFS than patients with tumours expressing higher levels of caspase-9 protein (p = 0.054, log rank test), although expression of caspases-8, -9 and/or -10 did not significantly predict RFS or OS." (PMID 25157404, 2014). "Our preliminary results show that there is a differential association of other partners to the complex caspase-9/PP2A between healthy and tumour cells which may explain this selective behaviour." (PMID 23637769, 2013). "Furthermore, chLym-1-induced autophagy can mediate apoptosis through Caspase 9 activation, demonstrating the tumor-suppressing role of autophagy in antilymphoma effects of chLym-1." (PMID 24015249, 2013). "TUSC2 and MK2206 induced tumor cell apoptosis via activation of caspase-9, as shown by its cleavage, however, whether this caspase is an essential downstream component of this activity is yet to be determined." (PMID 24146957, 2013). "The decrease in tumor size seen with PQ treatment may be attributed to an increase in apoptosis as the result of an up-regulation of caspase-3, caspase-8, and caspase-9." (PMID 23028705, 2012). "To study the effects of pardaxin on tumor functions, we performed a real-time RT-PCR analysis of caspase-3, caspase-7, caspase-8, caspase-9, Bax, Bcl-2, STAT2, ATF3, STAT3, SOCS3, IL-2, cathelicidin, TNF-α, MyD88, NF-κB1, p65, IFN-β1, IFN-γ, IL-1β, IL-6, IL-7r, and IL-10." (PMID 23015777, 2012). "Consistent with the immunohistochemical data, Western blot analysis of tumor proteins showed greater increased levels of cleaved caspase-3, cleaved caspase-9, cleaved PARP and Bax, whereas the levels of Bcl-2 and C-IAP1 were significantly decreased in CCR5−/− mice tissues." (PMID 22567084, 2012). "First, in-vitro co-incubation of WSX1-positive tumor cells reduces the number of T cells and induces a significant increase in caspase 8 and caspase 9 activation as well as an increase in late apoptosis markers mainly in CD8, and to a lesser extent, in CD4 T cells." (PMID 21559505, 2011). "It remains to be determined if MEK inhibitors would induce caspase 9 cleavage in tumor cells." (PMID 21637382, 2011). "Vpr has also been reported to activate caspase-9 and apoptosis in other human tumor cell lines." (PMID 19674438, 2009). "To examine whether Vpr and C81 target mitochondria in tumor cells, we measured caspase-8 and caspase-9 activity." (PMID 19674438, 2009). "In addition, there was significant induction of caspase-8 activity, and a much smaller induction of caspase-9 activity, indicating that EphB4 protects tumour cells from the extrinsic, membrane-originating apoptotic pathways." (PMID 17353927, 2007). "HGS-ETR1 reduced the viability of multiple types of tumour cells in vitro, and induced activation of caspase 8, Bid, caspase 9, caspase 3, and cleavage of PARP, indicating activation of TRAIL-R1 alone was sufficient to induce both extrinsic and intrinsic apoptotic pathways." (PMID 15846298, 2005). "Since the caspase-9 pathway was shown to be functionally involved in IR-induced apoptosis in other tumour models, the impaired activation of caspase-9 might contribute to the well-known resistance of RCC to IR-induced apoptosis." (PMID 12771998, 2003). "Moreover, BJP-2 could upregulate the expression of Bax, Cleaved Caspase-3/Caspase-3 and Cleaved Caspase-9/Caspase-9 and downregulation of Bcl-2, suggesting that the anti-tumor activity of BJP-2 is mediated through mitochondrial dependent pathways." (PMID 40308264, 2025). "Notably, it also increased caspase-9 activation, specifically in tumor cell lines." (PMID 38535442, 2024). "We also show that the PRSIM_23 CID module can be incorporated into a Caspase 9-based kill switch, enabling rapid induction of apoptosis in response to simeprevir, both in vitro, in multiple therapeutically relevant cell types, and in vivo in a xenograft tumor model." (PMID 38012128, 2023).
tumor (continued). "In addition, cleavage of caspase-9/-3 and PARP1 was increased in PI3/SLPI-deficient cells upon TRAIL treatment, substantiating the tumor-protective role of these two peptidase inhibitors through regulation of both intrinsic and extrinsic apoptosis pathways downstream of TSPO." (PMID 37158962, 2023). "Moreover, tumor cells have been shown to hijack the caspase-9 pathway in order to inhibit radiotherapy, which may improve radiotherapy sensitivity." (PMID 35846123, 2022). "Theoretically, inhibiting the CASP9 signaling pathway in combination with other drugs that promote endogenous cell apoptosis could also inhibit tumor therapy resistance and enhance anti-tumor immune responses." (PMID 35326602, 2022). "In our study, CASP9 was also found to be negatively associated with stromal score and the infiltration of immunosuppressive cells such as MDSCs in GBM, implying that CASP9 may also exert anti‐tumour effects by regulating the TIME of GBM." (PMID 35083859, 2022). "The present data provide in vivo evidence that inhibition of CRC tumour growth by KO may occur through the activation of intrinsic mitochondrial death pathway involving the increased release of Cyt c and activation of caspase-9 and caspase-3 leading to tumour cell death." (PMID 35236377, 2022). "Moreover, under the near-infrared laser irradiation, both in the tail vein injection group and the intratumoral injection group, a large area of necrosis in the tumor tissue, as well as the up-regulation of apoptotic proteins including cleaved caspase-3 and cleaved caspase-9 were observed." (PMID 36313308, 2022). "CuS-BSA NPs-mediated photothermal therapy could cause coagulative necrosis and up-regulate the expression of apoptosis proteins including cleaved caspase-3 and cleaved caspase-9, which inhibited tumor growth by inducing apoptosis to achieve photothermal therapy." (PMID 36313308, 2022). "Moreover, chemokines can sustain cancer cell survival by creating an imbalance between proapoptotic and antiapoptotic proteins in tumor cells (e.g., downregulation of Bcl-2 expression or inhibition of caspase-3 and caspase-9 activation), thereby avoiding tumor apoptosis." (PMID 34575965, 2021). "Furthermore, it also has the ability to promote tumor cell apoptosis (caspase-9 ↑, caspase-3 ↑)." (PMID 33013406, 2020). "CHB-II-F may be down-regulating the expression of Bcl-2 and up-regulating the expression of Bax, while activating both caspase-3 and caspase-9, fixing tumor cells in G0-G1 transition, increasing the rate of apoptosis of rumor cells and stimulating cells to initiate the process of apoptosis." (PMID 30670974, 2018). "In tumours derived from Lovo cells, we observed a trend to decrease caspase 9 expression and a significant decrease in Bax expression, suggesting that the increase in tumour size promoted by CNTD2 may reflect not only an increase in cell proliferation, but also a decrease in apoptosis." (PMID 30087414, 2018). "Compared to direct inhibition of NFκB activity, embelin, which potentiates apoptosis by relieving the inhibitory effect of XIAP on caspase 9 activity caused some increase in cell death, in particular in the interior of the spheroids although the tumor spheroid formation itself was not inhibited." (PMID 28460441, 2017). "Exogenous CNB was found to localize to mitochondria in tumor cells and activate the mitochondrial apoptosis pathway, as indicated by a decrease of mitochondrial transmembrane potential, release of cytochrome C and activation of caspase-9, which then activates caspase-3." (PMID 29029479, 2017). "Interestingly, previous studies have found that the exogenous expression of BubR1 induces apoptosis and inhibits expansion of tumours established with BubR1-depleted aneuploid cells in mice and that BubR1 triggers the intrinsic apoptotic pathway upstream of caspase-9, thereby activating caspase-3." (PMID 28410192, 2017).
tumor (continued). "Moreover, tumor homogenates prepared for western blotting showed there were significantly increased levels of acetyl-α-tubulin, acetyl-histone H3, cleavage form of caspase 9, and PARP as well as downregulation of FLIP expression in the MPT0G009 treatment group." (PMID 26587975, 2016). "Low levels of caspase-9 protein in primary tumour could therefore identify patients that are most likely to benefit from non-caspase-9 dependent treatments, such as death receptor (DR)-mediated apoptosis through caspase-8 cleavage and induction of the non-mitochondrial apoptotic pathway." (PMID 25157404, 2014). "In addition, we used shRNA and obtained results consistent with two the inhibitors, supporting the notion that CD133+ tumor cells preferentially activate the p38MAPK-MAPKAPK2-Hsp27 pathway probably through suppression of PP2A to inhibit caspase 9 and 3 cleavage." (PMID 23185379, 2012). "Deficient activation of caspase-9, therefore, might contribute to the clinically known resistance of human RCC against IR and also argues against an effective combination therapy with TRAIL and IR in this tumour type." (PMID 12771998, 2003). "Western blotting showed that SFP 2205 therapy improved Bad, Caspase-9, and Caspase-3 protein expression, and ultimately induced HEL tumor apoptosis, indicating mitochondrial pathway involvement." (PMID 37233483, 2023). "A recent study showed that the inhibition of CASP9 expression can mediate antitumor immunity, which benefits from the release of IFN-I in tumor cells after radiotherapy." (PMID 38025749, 2023). "The combinational drugs synergistically caused a significant imbalance in Bax/Bcl-2, and led to increased levels of caspase-3, caspase-9 and PARP-1, ultimately resulting in potent tumor suppression in BGC823 cell-xenografted mice." (PMID 37497002, 2023). "We found that Lan C induced a significant increase in caspase-9 and caspase-3 activity and a significant decrease in STAT3 expression in tumor tissues, consistent with the results in vitro experiments." (PMID 37397486, 2023). "Seven pyroptosis-related genes (ELANE, IL18, CHMP2B, CHMP4C, CASP9, CHMP6, and CHMP2A) were downregulated in tumor tissues, while 31 pyroptosis-related genes were upregulated in tumor tissues." (PMID 35432539, 2022). "Oil palm phenolic-induced apoptosis was associated with a decrease in Bcl-XL expressions, and increased cleaved caspase-3, caspase-9, and PARP expression, thus confirming the anti-tumor effects of these substances." (PMID 35276978, 2022). "The data demonstrated that TAX promoted the expression of the pro-apoptotic gene Bax, Caspase-3, and Caspase-9, and inhibited the expression of the anti-apoptotic gene Bcl-2 and oncogene Poly ADP ribose polymerase (PARP1) in SPC-A1 and LLC tumor cells." (PMID 36230568, 2022). "KO, and KO plus 1⁄2 dose of oxaliplatin significantly increased the expression of cytochrome c, cleaved caspase-9 and -3, and DNA damage and decreased expression of PD-L1, PD-L2 and HSP-70 in tumour tissues compared to the sham group." (PMID 35236377, 2022). "The administration of shikonin significantly enhanced the anticancer effect of ATO by upregulating caspase 3, caspase 9 activities, and the levels of CHOP mRNA, and MDA in tumor tissues." (PMID 36296934, 2022). "Previous studies have shown that CASP3, CASP9, and PYCARD are involved in tumor invasion and metastasis." (PMID 35845137, 2022). "This interfering peptide can modulate Caspase 9/PP2A interaction leading to a strong therapeutic effect in vitro and in vivo in mouse models of tumor progression." (PMID 36297489, 2022). "Our results showed that RTP significantly increases the expression of cleaved caspase-9 and cleaved caspase-3 proteins by 181% and 197%, respectively, in the RTP-H treatment group compared to the tumor group." (PMID 35269987, 2022).
tumor (continued). "This activation mediates the expression of the anti‐apoptotic gene Bclxl, which suppresses IR‐induced caspase 9 cleavage and maturation, thereby further inhibiting downstream caspase 7, caspase 3, and PARP cleavage and tumor cell apoptosis." (PMID 34738714, 2022). "The comparison showed that CASP3 and CASP9 were a higher expression in LGG, and CASP1 staining was consistent in tumor cells and glial cells." (PMID 35964070, 2022). "Previous studies have shown that interventional chemotherapy can promote tumor cell apoptosis; inhibit tumor growth, invasion, and metastasis; and improve prognosis by regulating the expressions of VEGF, Caspase-9, TNFAIP8, and Prdx4." (PMID 36476481, 2022). "We confirmed that heat-killed B. bifidum MG731, L. reuteri MG5346, and L. rhamnosus MG5200 increased the expression of caspase-9, and -3 and PARP in the tumor tissues." (PMID 36077182, 2022). "TAS4464 activated both caspase-8 and caspase-9 along with an increase in NOXA and a decrease in c-FLIP, resulting in complete tumor remission in a human AML xenograft model." (PMID 33420360, 2021). "Curcumin can induce tumor cell apoptosis by upregulating the expression of Caspase-9, Caspase-3, Caspase-7, and poly(adenosine diphosphate-ribose) polymerase (PARP), and it displays antineoplastic effects in tumor-bearing mice." (PMID 34239587, 2021). "Compared with the control group and single drug treatment group, the combination group of CPT and imatinib significantly promoted the cleavages of caspse-3, caspase-9 and PARP in tumour tissues." (PMID 34214017, 2021). "As previously reported, quercetin and crocetin were able to inhibit MAPK- or PI3K/AKT-mediated BCL-2 expression; promote the expression of caspase-3, caspase-8, caspase-9, and PARP so that tumor cells-cycle was inhibited, and apoptosis of tumor cell initiated." (PMID 34098848, 2021). "The PI-3K/AKT signaling pathway is important for tumor cells growth, and the phosphorylation of AKT directly blocks a variety of downstream targets, such as the proapoptotic proteins Bad, Bax, and Caspase-9." (PMID 33884026, 2021). "In summary, GSDME-dependent pyroptosis was revealed in CAP treated tumor cells, and mechanism study illustrated that the apoptotic pathway, ROS/Caspase-9/Caspase-3/GSDME, was activated in GSDME high-expressed tumor cells to initiate pyroptosis." (PMID 32341339, 2020). "Generally, miR-182-5p regulates the apoptosis of tumor cells by targeting certain special genes, such as FOXO1, MTSS1, HMGA2, CASP9, and FOXO3, and these target genes were also predicted by our experiment." (PMID 32090086, 2020). "A diminished caspase 9 activation was observed when miRzip-21 was -expressed in GBM8 and HCT116 tumor cells treated with siEGFR or siAKT in, the as compared to wildtype cells." (PMID 32019988, 2020). "This resulted in tumor cells undergoing apoptosis as indicated by higher levels of cleaved-PARP (cl-PARP) and activation of caspases 3/7 and caspase 9 in miRzip-21 expressing cells compared to scramble and untreated control cells." (PMID 32019988, 2020). "Immunoblotting of tumor tissues also showed similar patterns in the expression of HIF-1α, HIF-2α, VEGF, pro-caspase-9, pro-caspase-3 and cleaved PARP, compared with the in vitro results." (PMID 29946188, 2018). "When asking the same question using primary splenic MDSCs from MCA205 tumor-bearing WT or S100A4−/− mice, only cleaved caspase-3 and cleaved caspase-9 were increased in S100A4−/− MDSCs compared with levels in their WT counterparts." (PMID 29556233, 2018).